CLASRP (CLK4 associating serine/arginine rich protein)
Description:
Probably functions as an alternative splicing regulator. May regulate the mRNA splicing of genes such as CLK1. May act by regulating members of the CLK kinase family (By similarity).
Synonyms: SFRS16; SWAP2; CLASP
Tractability: PROTAC: its protein half-life has been measured.
Gene: Protein-coding gene on chromosome 19 (45,039,045 to 45,070,956, forward strand). Ensembl gene ENSG00000104859.
Subcellular location: Nucleus
Subcellular location (Human Protein Atlas): Nucleoplasm
Gene Ontology:
Molecular function: protein binding
Cellular component: nucleoplasm; nucleus
Genetic constraint (gnomAD): Loss-of-function variants: 44 observed, 80.99 expected, observed/expected ratio (o/e) 0.54, 90% interval 0.43 to 0.7. The upper end of that interval is the gene's LOEUF score, 0.7, which puts it in group 2 of 6, group 1 being the genes least tolerant of losing a copy. Missense variants: 794 observed, 896.4 expected, observed/expected ratio (o/e) 0.89, 90% interval 0.83 to 0.94. Synonymous variants: 357 observed, 326.61 expected, observed/expected ratio (o/e) 1.09, 90% interval 1 to 1.19.
Homologues: Orthologues: dog CLASRP (98% identical), pig CLASRP (97% identical), rabbit CLASRP (97% identical), guinea pig CLASRP (95% identical), rat Clasrp (95% identical), mouse Clasrp (95% identical), chimpanzee CLASRP (91% identical), macaque CLASRP (87% identical), tropical clawed frog clasrp (72% identical), zebrafish clasrp (69% identical), Drosophila melanogaster CG6695 (46% identical), Caenorhabditis elegans F28C1.1 (31% identical). Paralogues in human: SFSWAP (23% identical).
Diseases named in the same sentence as CLASRP in open-access papers:
CLASRP is named in the same sentence as 14 diseases in open-access papers, as found by Europe PMC text mining. Sharing a sentence is not in itself a finding about the gene and the disease. The quoted sentences say what the papers report.
head and neck cancer (2 papers, 2021 to 2023). A primary or metastatic malignant neoplasm affecting the head and neck. "As a candidate gene, CLASRP is an independent prognostic factor for patients with head and neck cancer, and it has been shown to have remarkable functions in cancer development." (PMID 37658940, 2023). "CLASRP has been shown to be relevant to the poor prognosis of patients with clear cell renal cell carcinoma and to be an independent prognostic factor for patients with head and neck cancer." (PMID 37658940, 2023). "Indeed, CLASRP is a prognostic predictor for head and neck cancer and clear cell renal cell carcinoma." (PMID 37658940, 2023).
clear cell renal cell carcinoma (1 paper, 2023). "Furthermore, CLASRP gene was found to be commonly up-regulated and this was correlated to a poor prognosis of clear cell renal cell carcinoma." (PMID 37658940, 2023).
colorectal cancer (1 paper, 2023). A primary or metastatic malignant neoplasm that affects the colon or rectum. "This study explored the biological function of CLASRP in colorectal cancer (CRC)." (PMID 37658940, 2023).
tumor (3 papers, 2012 to 2025). "The role of CLASRP in cell growth, the cell cycle and apoptosis during tumour progression was clarified through treatment with specific Clk inhibitors." (PMID 37658940, 2023). "The expression of CLASRP in tumour tissues of the cmv-CLASRP group was notably higher than that in tumour tissues of the control group (P < 0.05)." (PMID 37658940, 2023). "Nevertheless, the inhibitor TG003 effectively controlled the growth of tumours and suppressed the expression of CLASRP in vivo, suggesting that CLASRP is a promotional oncogene that could be regulated by Clk inhibitors." (PMID 37658940, 2023). "Functionally, overexpression of CLASRP significantly promoted the proliferation, migration and invasion of CRC cells in vitro and tumour growth in vivo." (PMID 37658940, 2023). "To investigate the correlation between inhibitors and CLASRP, we used the inhibitor TG003 in the in vivo antitumour evaluation of BALB/c nude mice with the DLD-1 tumour xenograft model." (PMID 37658940, 2023).
cancer (1 paper, 2023). A tumor composed of atypical neoplastic, often pleomorphic cells that invade other tissues. "Clk4-associated serine/arginine-rich protein (CLASRP), an alternative splicing regulator, may be involved in the development and progression of cancer by regulating the activity of the CDC-like kinase (Clk) family." (PMID 37658940, 2023). "Therefore, CLASRP maybe participates in the progression of cancers; however, very few reports have revealed the gene functions and significance of CLASRP." (PMID 37658940, 2023).
infection (1 paper, 2015). The state of being infected such as from the introduction of a foreign agent such as serum, vaccine, antigenic substance or organism. "Several infection-induced SUMO targets also are involved in mRNA maturation events, such as 3′ end pre-mRNA processing (CPSF1, CPSF2, FIP1L1, RBBP6, and WDR33), splicing (CLASRP, SFPQ, and ZRANB2), and nuclear RNA quality control (ZC3H18, ZCCHC7, and PAPD5)." (PMID 26549460, 2015).
lip (1 paper, 2019). "Similarly, when we combined the cleft lip only with the cleft lip and palate, we identified another significant dmCpG cg26985354 in gene CLASRP." (PMID 30832715, 2019).
neurodegenerative disease (1 paper, 2024). A disorder of the central nervous system characterized by gradual and progressive loss of neural tissue and neurologic function. "This included two known proteins associated with MERCS, MFN2 and TOMM40, as well as neurodegenerative disease-associated genes such as WIPI2, CLASRP, BAG6, SOD1 and FUS which increase MERCS and MTCH2 and PARL which decrease MERCS." (PMID 38467609, 2024).
CLASRP also shares sentences with these, for which no sentence is quoted: acute lymphoblastic leukemia (1 paper); esophageal squamous cell carcinoma (1); hepatocellular carcinoma (1); HIV-1 infection (1); injury (1); lung adenocarcinoma (1).